IRX1 (iroquois homeobox 1)
Diseases named in the same sentence as IRX1 in open-access papers (continued):
Sharing a sentence is not in itself a finding about the gene and the disease.
lung adenocarcinoma (1 paper, 2020). A carcinoma that arises from the lung and is characterized by the presence of malignant glandular epithelial cells. "In summary, our data suggest that IRX1 acts as tumor suppressor gene in the pathogenesis of lung adenocarcinoma and epigenetic silencing of IRX1 is associated with advanced stage and impaired prognosis of ADC patients." (PMID 33256112, 2020). "In our study, we analyzed the localization of IRX1 and we found that overexpression of IRX1 induced fragment nuclei in lung adenocarcinoma cells." (PMID 33256112, 2020). "Subsequently, we analyzed the epigenetic inactivation of IRX1 in 100 lung adenocarcinoma (ADC) and 100 squamous cell carcinoma (SQCC) and the corresponding control samples by bisulfite pyrosequencing and quantitative RT-PCR." (PMID 33256112, 2020). "Here, we report frequent epigenetic inactivation of IRX1 in primary lung adenocarcinoma (ADC)." (PMID 33256112, 2020). "In different datasets, we could validate that epigenetic silencing of IRX1 is clinically correlated with impaired survival and with progressed disease state of lung adenocarcinoma patients." (PMID 33256112, 2020). "We report frequent epigenetic inactivation of IRX1 in primary lung adenocarcinoma." (PMID 33256112, 2020). "Moreover, reduced expression and hypermethylation of IRX1 was correlated with an impaired prognosis of patients with lung adenocarcinoma." (PMID 33256112, 2020).
lung disease (1 paper, 2020). "Since there is evidence that epigenetic control plays a significant role in the pathogenesis of another lung disease (IPAH), we also analyzed IRX1 hypermethylation in IPAH samples." (PMID 33256112, 2020).
migraine (1 paper, 2025). "Our analyses revealed 283 genes, including some newly associated with migraine: MAML3, CELF4, IRX1, ASXL1, SPOCD1, CXCL, and TLR4." (PMID 41420111, 2025).
multiple sclerosis (1 paper, 2023). A progressive autoimmune disorder affecting the central nervous system resulting in demyelination. "In multiple sclerosis cases, IRX1-positive patients also had slower EDSS worsening [−0.07 points/year (−0.01,−0.13), P = 0.015] and lower risk of secondary progressive multiple sclerosis [OR = 0.19 (0.04–0.92), P = 0.042]." (PMID 37841069, 2023).
Myocardial fibrosis (1 paper, 2024). "CXCL14 exerts a synergistic effect with IRX1 to attenuate myocardial fibrosis and cardiomyocyte apoptosis." (PMID 38461325, 2024).
non-small cell lung carcinoma (1 paper, 2020). A group of at least three distinct histological types of lung cancer, including non-small cell squamous cell carcinoma, adenocarcinoma, and large cell carcinoma. "We observed frequent hypermethylation of the IRX1 promoter in non-small cell lung cancer (NSCLC) compared to small cell lung cancer (SCLC)." (PMID 33256112, 2020).
ovarian clear cell cancer (1 paper, 2025). An invasive malignant neoplasm that arises from the ovary and is characterized by a predominance of clear and hobnail malignant epithelial cells. "Interestingly, this phenomenon mirrors the findings in ovarian clear cell carcinoma, where ARID1A mutations are associated with promoter hypermethylation and transcriptional repression of downstream targets such as IRX1, TMEM101, and TRIP6." (PMID 41215803, 2025).
skin cutaneous melanoma (1 paper, 2023). "Higher expression of IRX1, IRX2, IRX3, IRX5, and IRX6 all display statistically significant unfavorable prognosis for skin cutaneous melanoma." (PMID 37084727, 2023).
squamous cell carcinoma (1 paper, 2020). A carcinoma arising from squamous epithelial cells. "In normal lung samples, the IRX1 promoter showed lower median DNA methylation levels (<10%) compared to primary adenocarcinoma (ADC, 22%) and squamous cell carcinoma (SQCC, 14%)." (PMID 33256112, 2020).
tumor (15 papers, 2014 to 2024). "The Iroquois homeobox protein 1 (IRX1) tumour suppressor gene is a cancer susceptibility locus." (PMID 36949543, 2023). "In contrast to previous models, in cervical cancer, high expression of IRX1 was found to be correlated with tumor staging." (PMID 36980893, 2023). "Functional data indicate that IRX1 acts as an epigenetically regulated tumor suppressor in different types of cancer." (PMID 33256112, 2020). "The upregulation of other homeobox transcription factors was also observed by us in cases of infratentorial tumor, which was shown to be connected with Iroquois homeobox transcription factors (IRX1, IRX2, IRX3, IRX5) and the PAX3 gene." (PMID 26497896, 2015). "Moreover, restoring IRX1 expression can reduce growth and invasion both in vivo and in vitro, calling attention to its function as a tumor suppressor gene." (PMID 36980893, 2023). "After the overexpression of IRX1 in HNSCC cells, a decrease in colonies and a reduction in cell number were observed, indicating the tumor suppressor activity of this gene." (PMID 36980893, 2023). "Among them, we identified and experimentally confirmed a group of methylation driver genes (e.g., PCDH17, IRX1, TBX5 and HSPB6) that play a critical role in neoplasia initiation, promotion, and progression." (PMID 33859751, 2021). "The IRX1 gene [10/14 (71%), 9/16 (56.25%) and 29/33 (88%)] demonstrated varying degrees of methylation on their promoter regions in normal mucosa, normal salivary rinses and HNSCC tumor samples, respectively." (PMID 24337411, 2014). "Although normal salivary methylation rate was observed as high, IRX1 methylation values were <1% in normal salivary rinses and were mostly (8/14, 57%) between 0.1 and 10% in normal mucosal samples indicating a very strong marker which may define HNSCC tumor tissues as a potential biomarker." (PMID 24337411, 2014).
cancer (13 papers, 2014 to 2025). A tumor composed of atypical neoplastic, often pleomorphic cells that invade other tissues. "We are also showing that IRX1 expression is negatively associated with oncogenic hallmarks by GSEA and that IRX1 expression induces signs of apoptosis in cancer cells, including fragmented nuclei and BAX levels." (PMID 33256112, 2020). "Additionally, we revealed that the reduced expression of IRX1 in cancer is linked to its promoter hypermethylation." (PMID 33256112, 2020). "Our results demonstrated that IRX1 was expected to be a potential target for the prevention and treatment of SAT loss in cancer cachexia." (PMID 36316707, 2022). "To analyze the methylation level of IRX1 in cancer-unrelated tissues, we utilized samples from idiopathic pulmonary artery hypertension (IPAH) patients." (PMID 33256112, 2020). "Next, we correlated the IRX1 hypermethylation at these three CpG sites (cg05534710, cg06689918, and cg09232937) with IRX1 downregulation in these cancer cell lines." (PMID 33256112, 2020). "As far as we know, the role of IRX1 in the progression of fat loss during cancer cachexia has not been elucidated." (PMID 36316707, 2022). "Cancer cell lines with low IRX1 methylation (<10%) exhibited the highest level of IRX1 mRNA levels." (PMID 33256112, 2020). "Interestingly, we observed that IRX1 was already downregulated in cancer cell lines that exhibited only low methylation levels." (PMID 33256112, 2020). "A significant IRX1 hypermethylation was observed for all three CpG sites in cancer cells." (PMID 33256112, 2020). "It suggested that the function of IRX1 may vary depending on the type of cancer cells." (PMID 38728457, 2024). "Therefore, we transfected IRX1 in cancer cells and analyzed the mRNA levels of BAX." (PMID 33256112, 2020). "Several hub genes were selected and IRX1 was presumed to contribute to the pathological difference between SAT and VAT in cancer cachexia." (PMID 36316707, 2022). "In the cancer cell lines SNB18, U343, U251, U118, and T47D on CTCFBS and the IRX1 promoter are unmethylated." (PMID 33256112, 2020). "In this scenario, the vast majority of CpG island promoter methylated genes represent passenger events with only a few true cancer driving events found in each case; in this context, DZIP1, COL4A2, L3MBTL4, IRX1 and RASSF10 are named as likely candidates." (PMID 25468711, 2015). "In contrast, other gene pairs, e.g. GRASP and NPY, or IRX1 and GRASP, or IRX1 and SDC2, are commonly methylated but show little correlation in measured levels of methylation within individual cancer samples." (PMID 24485021, 2014). "The DMRs identified when comparing LowHR HRpos-like samples and TNBCs included cancer-relevant genes such as EN1, TFF3 or IRX1 which have previously been described to be differentially methylated and expressed in TNBCs and hormone receptor positive breast cancers." (PMID 34602069, 2021). "Additionally, we utilized HeLa cancer cells and HEK293T cells to verify the shape of nuclei upon IRX1 transfection." (PMID 33256112, 2020). "For other genes or regions, e.g. DLX5, GRASP Region 3, IRX1, MMP2, NPY, PDX1 and TCF21, significant levels of methylation were evident in the matched normal tissue but methylation was always significantly increased in the cancer tissue." (PMID 24485021, 2014). "Other members of the Iroquois (IRO/IRX) family, IRX1, IRX3 and IRX5 have been found differentially methylated and/or expressed between supratentorial and infratentorial PAs, suggesting that these genes may have an important role in specific location cancer development." (PMID 29568396, 2018).
cardiovascular disease (2 papers, 2023 to 2025). "A putative role of the IRX1 locus in vasodilation/vasoconstriction might also explain its association with cardiovascular disease as described among people of East Asian descent." (PMID 37828025, 2023).
infection (2 papers, 2015 to 2023). The state of being infected such as from the introduction of a foreign agent such as serum, vaccine, antigenic substance or organism. "Infection with H. pylori and inactivation of IRX1 genes via promoter methylation or allelic loss seem to be common events related to IRX1 in the development of gastric carcinogenesis." (PMID 36980893, 2023). "IRX1 was also up-regulated in the same genotype BGE015746 in response to the infection with rust, suggesting that the induction of this cellulose synthase, and consequently cell wall strengthening, may play an important role in resistances of this grass pea genotype to diverse pathogens." (PMID 25852725, 2015).
adenocarcinoma (1 paper, 2020). A common cancer characterized by the presence of malignant glandular cells. "In adenocarcinoma (ADC), we observed frequent increased methylation of the IRX1 promoter and reduced RNA levels." (PMID 33256112, 2020).
IRX1 also shares sentences with these, for which no sentence is quoted: acute lymphoblastic leukemia (2 papers); congenital heart disease (2); B-cell precursor acute lymphoblastic leukemia (1); colorectal cancer (1); craniosynostosis (1); endometrial cancer (1); gastric tumors (1); glioma (1); Hypertension (1); Kyphoscoliosis (1); lymphoma (1); melanoma (1); Mendelian diseases (1); metabolic disease (1); myeloid leukemia (1); Obesity (1); periodontitis (1); rheumatoid arthritis (1); scoliosis (1); secondary progressive multiple sclerosis (1); small cell lung carcinoma (1); squamous cell carcinoma of the lung (1); T-cell ALL (1).